RBMY1A1 (RNA binding motif protein Y-linked family 1 member A1)
Description:
RNA-binding protein involved in pre-mRNA splicing. Required for sperm development. Acts additively with TRA2B to promote exon 7 inclusion of the survival motor neuron SMN. Binds non-specifically to mRNAs.
Synonyms: RBM1; RBM2; YRRM1; YRRM2; RBM; RBMY; RBMY1C
Tractability: No criterion of Open Targets' tractability assessment is met for any kind of drug.
Gene: Protein-coding gene on chromosome Y (21,534,879 to 21,549,326, forward strand). Ensembl gene ENSG00000234414.
Subcellular location: Nucleus
Subcellular location (Human Protein Atlas): Nucleoplasm; Nucleoli
Gene Ontology:
Molecular function: mRNA binding; protein binding; nucleic acid binding; RNA binding
Biological process: regulation of alternative mRNA splicing, via spliceosome; mRNA splicing, via spliceosome
Cellular component: spliceosomal complex; nucleus
Homologues: Orthologues: macaque RBMY (35% identical), rat Rbmy1j (34% identical), mouse Rbmyf9 (32% identical), mouse Rbmyf2 (32% identical), mouse Rbmyf3 (32% identical), mouse Rbmy (32% identical), mouse Rbmyf1 (32% identical), mouse Rbmyf5 (32% identical), mouse Rbmyf6 (32% identical), mouse Rbmyf7 (32% identical), mouse Rbmyf8 (32% identical), mouse Rbmyf4 (17% identical). Paralogues in human: RBMY1D (99% identical), RBMY1B (99% identical), RBMY1E (99% identical), RBMY1F (99% identical), RBMY1J (99% identical), RBMX (48% identical), RBMXL1 (46% identical), RBMXL2 (38% identical), RBMXL3 (31% identical), CIRBP (17% identical), RBM3 (14% identical), MSI1 (14% identical), and 24 more.
Diseases named in the same sentence as RBMY1A1 in open-access papers:
RBMY1A1 is named in the same sentence as 12 diseases in open-access papers, as found by Europe PMC text mining. Sharing a sentence is not in itself a finding about the gene and the disease. The quoted sentences say what the papers report.
seminoma (1 paper, 2025). A radiosensitive malignant germ cell tumor found in the testis (especially undescended), and extragonadal sites (anterior mediastinum and pineal gland). "Additionally, focal deletions targeting the RBMY gene family (RBMY1A1, RBMY1B, RBMY1D)—male germ cell–specific RNA-binding proteins—were significantly enriched in seminomas (26.6% vs. 12.8% in non-seminomas; P = 0.0078)." (PMID 40568177, 2025).
tumor (5 papers, 2011 to 2022). "We found a total of 16 RBPs that could match to lncRNA-n326322, including RBMY1A1, EIF4B, and Pum2, which have been reported to have an important influence on tumor progression." (PMID 29416735, 2018).
RBMY1A1 also shares sentences with these, for which no sentence is quoted: hepatoma (4 papers); liver cancer (4); male infertility (4); cancer (3); Azoospermia (1); breast carcinoma (1); Cirrhosis (1); hepatoblastoma (1); infertile (1); prostate carcinoma (1).